INS (insulin)
Diseases named in the same sentence as INS in open-access papers (continued):
Sharing a sentence is not in itself a finding about the gene and the disease.
Hypoglycemia (continued). "Reduction in the incidence of hypoglycemia was found for all GLP-1 RAs versus insulin (except for dulaglutide) and sulphonylureas." (PMID 27158818, 2016). "We demonstrate that insulin-induced hypoglycemia significantly reduced GJ-mediated intercellular transfer of Lucifer Yellow." (PMID 27034963, 2016). "Plasma levels of glucagon, the most important hormone involved in achieving recovery of glucose levels following acute hypoglycemia, were similar in WT and KO mice 60 min after insulin injection (time when WT mice had started to normalize their glycemia)." (PMID 27148080, 2016). "CKD is associated with several disorders of insulin and carbohydrate metabolism and when renal failure advances, insulin clearance decreases, demanding a dose reduction to prevent hypoglycemia." (PMID 26872083, 2016). "While, the beneficial hypoglycemia lowering effect of all GLP-1 RAs was observed when compared with insulin (except for dulaglutide) and SU, which was consistent with previous reviews and clinical trials." (PMID 27158818, 2016). "Congenital hyperinsulinism (CHI) is a rare condition of hypoglycemia (reported incidence of severe CHI, 1:30,000–1:50,000) due to unregulated and excessive insulin secretion with the potential to cause hypoglycemia-related brain injury." (PMID 26903946, 2016). "Combination treatment with MET and JTXK 3.5 g/kg increased the hypoglycemia and insulin sensitivity at 4 weeks when compared with the DM mice treated with MET alone." (PMID 27418937, 2016). "An observational study in the United States has shown that adherence to insulin therapy increases and incident hypoglycemia decreases when patients are switched from the traditional vial and syringe system to insulin analog pen devices." (PMID 27278922, 2016). "Iatrogenic hypoglycaemia is an acute complication in both type 1 and type 2 DM and is because of the use of oral sulphonylureas and insulin in the management of DM." (PMID 27380790, 2016). "As a consequence, with the progression of CKD, insulin clearance decreases, thus requiring a dose reduction in order to avoid hypoglycemia." (PMID 27471550, 2016). "Though we established another mouse model, control mice with insulin pellets, all died because of severe hypoglycemia before analyses." (PMID 27846299, 2016). "A significant relation was found between dose of insulin, amount of snacking, and severity of hypoglycemia." (PMID 27994961, 2016). "However parental worry about hypoglycaemia is also associated with elevated HbA1c among children, suggesting that parents may overcompensate in their attempts to avoid hypoglycaemia (e.g. by reducing insulin doses)." (PMID 27519408, 2016). "Other seven patients with negative results of 99mTcGLP-1 scintigraphy and postprandial hypoglycemia with C-peptide and insulin levels within the limits of normal ranges are in the observational group." (PMID 27526057, 2016). "Some reluctance to initiate or intensify insulin therapy has been noted among patients and physicians because of fear of hypoglycemia and weight gain, and perceived problems of dependency on the medication and complexity of titration and injection regimens." (PMID 27760129, 2016). "The increase was more pronounced in the 2 months old mice, in agreement with the more pronounced hypoglycemia induced by insulin administration." (PMID 27685945, 2016). "The unregulated insulin secretion promotes glucose uptake into the skeletal muscles, liver, and adipose tissue, exacerbating the hypoglycemia further." (PMID 27065949, 2016). "Many patients with T2DM are often treated with insulin early in the disease process, in spite of the availability of multiple classes of antidiabetic agents with extremely low risks of hypoglycemia." (PMID 27417914, 2016). "The objective of this present research was to study the molecular mechanisms of acute neuropathic pain induced by insulin and hypoglycemia in an animal model." (PMID 26824041, 2016).
Hypoglycemia (continued). "In two U.S. representative surveys over a 4 year period, Geller and al. estimated there were nearly 100,000 emergency department visits per year for insulin-related hypoglycaemia and errors, among which almost one-third required hospitalization." (PMID 27391319, 2016). "A significant correlation was found between dose of insulin, amount of snacking, and severity of hypoglycemia." (PMID 27994961, 2016). "Second, up to now, little attention was paid to the study of carbohydrate counting’s effect on hypoglycemia events, insulin doses and BMI." (PMID 27841330, 2016). "When the nutritional source was removed, hypoglycemia tended to occur at higher Lispro insulin doses." (PMID 26819233, 2016). "The nocturnal time spent with hypoglycaemia with the bihormonal system was significantly reduced compared with the insulin-alone system (p = 0.032)." (PMID 27364997, 2016). "The presence of a previous episode of hypoglycemia as well as the choice of antidiabetic therapy, in particular in patients receiving complex insulin regimens, has consistently been reported as a strong predictor of hypoglycemia." (PMID 26887662, 2016). "Impaired awareness of hypoglycemia is a commonly reported condition in patients who use long-term insulin." (PMID 27994961, 2016). "On some days glucose was also measured more frequently between insulin injections; for example every 3 h or when hypoglycaemia was suspected)." (PMID 27766967, 2016). "The group that had experienced severe hypoglycemia symptoms used significantly higher doses of insulin per day than other groups." (PMID 27994961, 2016). "In hyperinsulinemic hypoglycemia (HH), this precise regulation of insulin secretion is perturbed so that insulin continues to be secreted in the presence of hypoglycemia." (PMID 27065949, 2016). "Among these studies, the annual hypoglycemia-related medical costs in those treated with insulin were $1,528, compared to $620 for those treated with insulin analogues." (PMID 26890789, 2016). "Although many insulin-based regimens have been used safely in elderly patients, hypoglycemia is a concern and presents a challenge for obtaining optimal glycemic control." (PMID 27246619, 2016). "The amplified risk for hypoglycaemia in CKD is well documented, especially for patients treated with insulin or sulfonylureas." (PMID 27286816, 2016). "The dosage of insulin to induce antecedent and subsequent hypoglycaemia in healthy individuals in most studies ranged from 1 to 2 mU/kg/min." (PMID 27843452, 2016). "The nocturnal HBGI and CONGA2, along with HbA1c and daily insulin dose, were predictors of LF during daytime hypoglycemia in multiple regression analysis." (PMID 27066358, 2016). "Factors that are associated with an increased risk of hypoglycemia in DKD patients include decreased renal gluconeogenesis, deranged metabolic pathways (including altered metabolism of medications) and decreased insulin clearance." (PMID 27471550, 2016). "The group that had experienced moderate hypoglycemia symptoms used significantly higher doses of insulin and snacked more times per day than other groups." (PMID 27994961, 2016). "Regarding NOD animals, the delayed hypoglycemia can be explained by the higher glucose levels required to be controlled, and the prolonged hypoglycemia (2 h) by the higher rates of insulin production." (PMID 27660634, 2016). "These tend to focus on individuals using insulin and their results indicate that severe hypoglycaemia prevalence is below 1%, which is substantially lower than our pooled estimate of 6% from population-based studies." (PMID 26061690, 2015). "In other words, our findings identified correctable factors (i.e., assistance from family members and current drinking) that exist for the prevention of hypoglycemia in insulin treated diabetic patients." (PMID 26102197, 2015).
Hypoglycemia (continued). "Patients were reviewed after 12 weeks and baseline to endpoint changes in glycated hemoglobin (A1C), insulin doses, body weight and incidence of hypoglycemia were compared by paired and independent Student t-tests." (PMID 25904987, 2015). "Some insulin pump estimates the IOB to correct the boluses in order to avoid hyper- or hypoglycemia." (PMID 26550021, 2015). "The insulin type, dose and administration must be tailored to each patient to achieve goal glycemic levels but limit hypoglycemia." (PMID 28702221, 2015). "The event rates for severe hypoglycaemia in insulin-treated patients as reported in the literature and expressed as episodes per 100 patient-years range from 62 to 320 in type 1 (T1) DM, and from 0 to 73 in T2 DM." (PMID 26458540, 2015). "The hypoglycaemia alarms are designed to operate in instances when impending hypoglycaemia cannot be avoided by holding insulin alone." (PMID 26581230, 2015). "This method reveals the parameters that require therapeutic action; for example, the adjustment of the insulin therapy in the case of hypoglycaemia." (PMID 25929322, 2015). "Objective.To assess the effectiveness of a nurse-managed protocol to prevent hypoglycemia during subcutaneous insulin treatment." (PMID 25961051, 2015). "It is well recognized the main positive and proved effects of insulin analogues on hypoglycemia reduction, glucose peaks and improvement in quality of life of DM1 patients." (PMID 26288660, 2015). "Blinding to treatment allocation would lead to suboptimal glucose levels control with excessive rate of hypoglycemia, and therefore, open-labeled design is justified in studies assessing insulin therapy." (PMID 25585592, 2015). "We have done continuous glucose monitoring on patients undergoing HD and found that patients’ glycemic responses during HD are quite idiosyncratic and their insulin regimens need to be individualized to avoid both hyper-and hypoglycemia during and after HD." (PMID 28702221, 2015). "A 6-h fast produced hypoglycemia (glucose levels of 40 mg/dL), with insulin levels of 21 μU/mL and C-peptide levels of 3.14 ng/mL." (PMID 26107678, 2015). "In the current study, we observed that the addition of acarbose to insulin improves glucose fluctuation in patients with T2DM, as measured by MAGE, and reduced the risk of severe hypoglycemia." (PMID 26640487, 2015). "On the other hand, if DPP4 inhibitors are combined with premixed insulin preparations or bolus insulin, it is necessary to adjust the insulin dose, particularly that of bolus insulin, to avoid hypoglycemia." (PMID 25780477, 2015). "The precise role of hypersecretion of insulin by primed islet beta cells and of dissociation of the insulin–antibody complex in an individual case of symptomatic hypoglycemia has been studied infrequently." (PMID 26241232, 2015). "Consistent with this pharmacological action, BEGIN Basal-Bolus Type 1 Trial showed that the rate of nocturnal-confirmed hypoglycemia was 25% lower with insulin degludec than with insulin glargine." (PMID 26435713, 2015). "Annual admission rates for hypoglycemia per 1000 diabetic patients and 1000 diabetic patients receiving insulin or oral hypoglycemic agents were 2.1 and 4.1, respectively." (PMID 26107672, 2015). "A proof of concept study showed that the SGLT2 inhibitor empagliflozin when added to insulin therapy improved glycemic control in type 1 diabetic subjects while lowering the insulin dose and body weight as well as the frequency of hypoglycemia." (PMID 25785209, 2015). "After 90 days, all symptoms attributable to hypoglycemia disappeared, and plasma glucose and insulin levels were in the normal range." (PMID 25816027, 2015). "Patients who had used SU agents or insulin had significantly more knowledge of hypoglycemia than those being treated with other drugs (P < 0.001)." (PMID 26566411, 2015).
Hypoglycemia (continued). "Three-week-old rats were subjected to five episodes of insulin-induced moderate hypoglycemia (blood glucose concentration, 1.7 ± 0.7 mmol/L (31 ± 15 mg/dL)), once daily from P24 and P28." (PMID 26343738, 2015). "Because hypoglycaemia became milder at the end of our study in the glucose plus insulin group compared to the insulin group, the death rate was seemingly largely dependent on the severity of hypoglycaemia." (PMID 26366172, 2015). "In reports dealing with severe hypoglycemia, background factors included advanced age, decreased renal function, SU agents, and insulin use." (PMID 26566411, 2015). "Hypoglycemia is a common problem in diabetic patients with antidiabetic therapies, especially in those receiving insulin treatment." (PMID 25961056, 2015). "Generally, the hypoglycemia attacks relieved in parallel with the decrease in the titer of the IAb and serum insulin level after insulin therapy was discontinued." (PMID 25961056, 2015). "Hypoglycemia is a common side-effect of insulin and sulfonylurea therapy, impairing many cognitive domains necessary for safe driving performance." (PMID 28702227, 2015). "In the current study, patients presented with unexpected hypoglycemia even after discontinuation of insulin and with obvious insulin-C-peptide separation in insulin and C-peptide release test." (PMID 25961056, 2015). "Hypoglycaemia is particularly prevalent amongst those on insulin, yet still fairly common for treatment regimens that do and do not include sulphonylureas." (PMID 26061690, 2015). "Hypoglycemia is one of the most common acute complications in insulin-treated diabetes and is indicated to be an important limiting factor for glycemic control in type 1 diabetes." (PMID 25599725, 2015). "Clinically, oral antidiabetics have diverse side-effects, and treatment with insulin has revealed risks of weight gain and hypoglycemia." (PMID 25574213, 2015). "IDeg is an ultra-long insulin analog that exhibits low intra-individual variability and whose efficacy is comparable to IGlar, but which presents as advantages flexibility in dose timing and lower risk of hypoglycemia, benefits that may impact quality of life and adherence to therapy." (PMID 26136850, 2015). "On starting insulin, the dose of sulphonylureas should be reduced to prevent hypoglycaemia, whilst other oral hypoglycaemic agents can be continued." (PMID 26550039, 2015). "It found that patients randomized to the treatment with insulin analogues (detemir and aspart) experienced less hypoglycemia than those randomized to treatment with human insulins (NPH and regular)." (PMID 25964802, 2015). "Previous reports have identified glycemic control, type of insulin therapy, and frequency of hypoglycemia as factors influencing QOL." (PMID 26819737, 2015). "In the present study, ablation of the fetal adrenal medullae at 98 dGA decreased the NE responsiveness to hypoglycemia and hypoxemia at 134 dGA, but plasma insulin concentrations remained low because the prior conditions of placental insufficiency." (PMID 25584967, 2015). "If unexpectedly recurrent hypoglycemia occurred, especially after insulin had been discontinued for several days, immunological hypoglycemia associated with IAbs due to exogenous insulin should be considered." (PMID 25961056, 2015). "In Cox regression analyses adjusting for potential confounders, premixed insulin (hazard ratio, HR: 2.12) and rapid acting insulin (HR: 2.75) showed significantly higher risks of severe hypoglycaemia compared with a long-acting insulin analogue." (PMID 25698911, 2015). "The technical problem can result in higher insulin dose calculation and can result in severe hypoglycemia." (PMID 28702234, 2015). "It is thus possible that the reduced frequency of nocturnal hypoglycaemia observed during IDeg treatment in previous studies is attributable to the low variability of the glucose-lowering effect of this insulin analogue revealed by the present study." (PMID 26044206, 2015).
Hypoglycemia (continued). "The density of hypoglycemia was 0.30 events per day of insulin therapy and 0.15 events per day in the ICU." (PMID 25888011, 2015). "The objective of this study was to explore predictors, including social factors, lifestyle factors, and factors relevant to glycemic control and treatment, for mild and severe hypoglycemia in insulin-treated Japanese diabetic patients." (PMID 26102197, 2015). "Autonomic nerves are essential components of the endogenous system for maintaining energy homeostasis during renal gluconeogenesis under insulin-induced hypoglycemia." (PMID 26564063, 2015). "They will still need to treat (rare) hypoglycaemia with carbohydrates, change the insulin catheter and sensor, or check the blood glucose for sensor calibration." (PMID 26581230, 2015). "Women with BMI > 30 had more neonatal complications in insulin treated group as compared to metformin treated group indicating protective effect of metformin in reducing neonatal hypoglycemia and thus NICU admissions." (PMID 25874236, 2015). "Hypoglycemia remains a common problem with insulin and has an estimated prevalence of 12 % even in academic medical centers." (PMID 28702223, 2015). "Other reports show that infection by T. spiralis induces host hypoglycemia and suggest that this is the result of an increase in glucose uptake by infected muscle cells via up-regulation of the insulin signaling pathway." (PMID 26720604, 2015). "In the non-obese subjects, the DM duration, incidence of hypertension, incidence of hypoglycemia episodes and insulin usage were higher in the CAD group, whereas these differences were not significant between the groups in the obese subjects." (PMID 26098780, 2015). "According to the report regarding severe hypoglycemia such as hypoglycemic coma in emergency visit, three major factors are advanced age, renal function degeneracy, and sulfonylurea (SU) agent or insulin use." (PMID 26566411, 2015). "By contrast, glucagon secretion is required in type 1 diabetes to ensure an adequate response to insulin-induced hypoglycemia, and a failure of this process contributes significantly to mortality in the latter disease." (PMID 26178371, 2015). "Assessment methods in different publications include basal cortisol concentrations, low-dose ACTH stimulation (1 mcg), standard dose ACTH stimulation (250 mcg), metyrapone, glucagon, and insulin hypoglycemia." (PMID 26287247, 2015). "Longer duration of insulin treatment, previous hypoglycaemia using oral drugs, and history of TIA/stroke were also independently related to an increased odds." (PMID 25698911, 2015). "Most of those studies explored hemostatic effects of symptomatic insulin-induced severe hypoglycemia." (PMID 25928628, 2015). "In both cases, the action of insulin boluses was too slow with regard to the requirements of patients, leading to the appearance of late worrisome hypoglycemia." (PMID 25614824, 2015). "In anesthetized, paralyzed and artificially ventilated rats, local CBF was markedly increased in most regions of the brain during insulin-induced hypoglycemia." (PMID 26528968, 2015). "In the first study, Moore and colleagues induced insulin-induced moderate hypoglycemia (blood glucose concentration, 1.6–2.2 mmol/L (30–40 mg/dL) for approximately 3 h) twice daily from P10 to P19 (20 episodes)." (PMID 26343738, 2015). "We found that patients using insulin and SU agents have a higher level of knowledge of hypoglycemia than patients using other drugs." (PMID 26566411, 2015). "It was previously shown that insulin-induced severe hypoglycemia in healthy subjects promotes platelet aggregation." (PMID 25928628, 2015). "The incidence of hypoglycemia was investigated in 7,855 patients using SU agents or insulin; the incidence of hypoglycemia increased in both the groups with low and high HbA1c." (PMID 26566411, 2015).